RNU6-1167P (RNA, U6 small nuclear 1167, pseudogene)
Gene: Small nuclear RNA gene on chromosome 10 (35,250,959 to 35,251,052, reverse strand). Ensembl gene ENSG00000200097.
Homologues: Orthologues: chimpanzee U6 (100% identical), macaque U6 (95% identical), guinea pig U6 (74% identical). Paralogues in human: RNU6-403P (83% identical), RNU6-1124P (82% identical), RNU6-621P (82% identical), RNU6-737P (82% identical), RNU6-1316P (81% identical), RNU6-20P (81% identical), RNU6-25P (81% identical), RNU6-29P (81% identical), RNU6-35P (81% identical), RNU6-434P (81% identical), RNU6-517P (81% identical), RNU6-641P (81% identical), and 1287 more.